IRS2 (insulin receptor substrate 2)
Diseases named in the same sentence as IRS2 in open-access papers (continued):
Sharing a sentence is not in itself a finding about the gene and the disease.
breast carcinoma (continued). "Thus, it would be important to have more studies and samples from other ethnicity so that more accurate conclusions about the relationship between the IRS2 rs1805097 polymorphism and colorectal and breast cancer risk might be determined." (PMID 24497996, 2014). "PLK1, IFNG, S100B, and IRS2 were expressed at significantly different levels between breast cancer and normal breast tissues." (PMID 39314848, 2024). "[Δ: Percentage of Dkk1-IRS reduction, IRS1: Dkk1-IRS in core needle biopsy tissue, IRS2: Dkk1-IRS in mammary carcinoma tissue]." (PMID 38254908, 2024). "In breast cancer, IRS2 contributes to both the initiation of primary tumor growth and the establishment of secondary metastases through regulation of cancer stem cell (CSC) function and invasion." (PMID 39305958, 2024). "The expression levels of S100B and IRS2 in breast cancer tissues were significantly lower than those in the paired adjacent normal tissues." (PMID 39314848, 2024). "Through analysis of these models, a role for IRS2 in regulating breast cancer progression and metastasis has been revealed." (PMID 39305958, 2024). "IRS2 is expressed at high levels in breast carcinoma cells of the basal-like/triple-negative breast cancer (TNBC) subtypes, and it regulates tumor cell migration, invasion, and glycolytic metabolism." (PMID 36975518, 2023). "This correlates with several reports on neuroblastoma and breast cancer, where the overexpression of IRS-2 promoted cell motility, invasion, and metastasis." (PMID 36975518, 2023). "IRS-2-expressing breast carcinoma cells are less invasive after treatment with an IGF-1R/IR small molecule inhibitor, which emphasizes the importance of upstream IGF-1R signaling through IRS-2 for the regulation of invasion." (PMID 36556357, 2022). "Targeting IRS-2, in particular, is intriguing as it is highly expressed in more aggressive breast cancers for which there are few effective treatments." (PMID 36556357, 2022). "Our findings are in line with the literature, in which upregulation of IRS2 promoted glucose uptake and glycolysis in mammary tumor cells and chronic myelogenous leukemia cells." (PMID 35816477, 2022). "We interrogated the TCGA provisional dataset for association of gene expression alterations in the IGF signalling components analysed above (IGF-1R, IFG-2R, IGFBP4, IRS-1, IRS-2) with survival in breast cancer." (PMID 32792532, 2020). "Antibody specificity for IRS-2 was validated by staining MDA-MB-231 breast carcinoma cells that expressed an IRS-2 specific shRNA." (PMID 31393907, 2019). "In mouse models, a role for Irs-2 in progression is demonstrated by the finding that knockout of Irs-2 expression inhibits PyMT-driven mouse mammary tumor metastasis and also suppresses tumor progression in Pten-/+ mice." (PMID 31393907, 2019). "The proteosomal degradation of IRS1 and IRS2 is blocked by interactions with the ERα in a breast cancer cell line." (PMID 29868002, 2018). "We demonstrated that mTORC1 inhibition with RAD001 (everolimus) induces IGF-1R/InsR/IRS-1/IRS-2-dependent activation of PI3K/AKT signaling in ER+ breast cancer cells and human tumors treated ex vivo." (PMID 29507656, 2018). "Using mouse models of breast cancer, it was shown that overexpressing IRS2 lead to mammary hyperplasia, tumorigenesis, and metastasis." (PMID 29868002, 2018). "IRS-null breast cancer cells (T47D-YA) were engineered to express IRS-1 or IRS-2 alone and their ability to mediate IGF ligand-induced proliferation, motility, and gene expression determined." (PMID 26991655, 2016). "To examine the biological significance of IRS-induced gene expression, we evaluated the induction of TGFβ mRNA by both IRS-1 and IRS-2 in breast cancer cells." (PMID 26991655, 2016). "Substantiating this, overexpression or knockdown of IRS1 or IRS2 in MMTV-ErbB2 mammary cancer cell lines had little effect upon ErbB2 signaling." (PMID 27765041, 2016).
breast carcinoma (continued). "These genes include: transcription factor Dp-1 (TFDP1), cullin 4A (CUL4A), and cell division cycle 16 (CDC16) identified in hepatocellular carcinoma (HCC), breast cancer, and lung cancer; and insulin receptor substrate 2 (IRS2) present in colorectal cancer." (PMID 26684807, 2015). "Overexpression of IRS2 increases colorectal cell adhesion, similar to observations made for breast cancer." (PMID 26684807, 2015). "Cumulative evidence suggests that IRS-2 is overexpressed in pancreatic adenocarcinoma, breast cancer and colorectal cancer." (PMID 24810113, 2014). "In the present study, we analyzed the coding region and short intron-exon borders of the insulin receptor substrate 1 and 2 (IRS-1 and IRS-2) genes in 12 cell lines derived from breast cancer (BC), 14 cell lines derived from CRC and 33 primary CRCs." (PMID 23877285, 2013). "Insulin receptor substrate 2 (IRS-2) is regulated by hypoxia to promote breast carcinoma cell survival and invasion." (PMID 23241400, 2012). "An alternative mechanism for the differential involvement of IRS-1 and IRS-2 in cancer that would allow for the activation of a common signaling pathway by these adaptor proteins was revealed during the analysis of Irs1-/- mammary tumors." (PMID 19534786, 2009). "In contrast, breast cancer cells selected for metastatic behaviour in vivo have increased IRS-2 activation." (PMID 17043687, 2006). "Previous work in our lab suggests a role for IRS-2 in mediating cell motility in highly metastatic breast cancer cell lines." (PMID 17043687, 2006). "Insulin receptor substrate-1 and IRS-2 were expressed in T47D-YA breast cancer cells, which lack IRS-1 and -2 expression, yet retain functional IGF-IR." (PMID 17043687, 2006). "The results showed that the expression of PLK1 and IFNG in human breast cancer cells were significantly higher than in human normal mammary epithelial cells; while the expression of S100B and IRS2 were significantly lower than in human normal mammary epithelial cells." (PMID 39314848, 2024). "In contrast, in ER- breast carcinoma cells, IRS-2 plays a dominant role in CSC regulation." (PMID 36556357, 2022). "In addition, IGF-1 enhances IRS-2 phosphorylation to a greater degree than IRS-1 in metastatic mammary tumor cells, and knockdown of IRS-2 expression reduces IGF-mediated motility in vitro." (PMID 36556357, 2022). "IRS-2 is an important modulator of aerobic glycolysis in mouse mammary cancer cells." (PMID 24980829, 2014). "Oestrogens may also regulate IGF-stimulated cell migration via increased IRS-1 and IRS-2 expressions as these are both involved in breast cancer cell migration." (PMID 23983688, 2013). "IGF1 promotes cell motility in human breast carcinoma cell lines that predominately express IRS2." (PMID 23112878, 2012). "IRS-2, like IRS-1, can promote tumor initiation and progression when this adaptor protein is overexpressed in the mammary gland, a finding that would appear to conflict with the inability of IRS-2 to regulate tumor proliferation in human breast carcinoma cell lines." (PMID 19534786, 2009). "None of the other IRS2 SNPs genotyped in Cancer Genetic Markers of Susceptibility were associated with breast cancer, including those that were highly correlated with SNPs in our study." (PMID 18611262, 2008). "But the drug sensitivity of IRS2 amplification in breast cancer remains unclear." (PMID 38750402, 2024). "Moreover, IGF signalling via IRS2 is known to be essential for breast cancer cell migration." (PMID 36034422, 2022). "In conclusion, this meta-analysis suggests that the IRS2 rs1805097 polymorphism may not contribute to the colorectal and breast cancer risk." (PMID 24497996, 2014). "Therefore IRS-1 and IRS-2 are most likely implicated in CRC and breast cancer (BC)." (PMID 23877285, 2013). "Interestingly, IRS-2 was identified as a positive regulator of metastasis in breast cancer, whereas IRS-1 may be a suppressor of metastasis." (PMID 23251408, 2012).
breast carcinoma (continued). "At least two previous studies have examined whether IRS2 SNPs are associated with breast cancer, but neither found an association." (PMID 18611262, 2008). "Our findings suggest that these tagging SNPs in HSD11B1 and IRS2 mark regions of the genome that may harbor risk alleles for breast cancer, and these associations are probably independent of adiposity." (PMID 18611262, 2008). "However, IRS-2 is recruited to and activated by additional surface receptors, including integrins, growth hormone receptor and cytokine receptors, suggesting that membrane IRS-2 staining in breast cancer could represent activity of IGF-1R-dependent and -independent pathways." (PMID 36556357, 2022). "The presence of IRS2 inhibited the ability of IRS1 to sensitize myeloblast-like and breast cancer cells to taxol, etoposide, and vincristine therapy and silencing of IRS2 potentiates the effects of ruxolitinib in myeloproliferative neoplasms cells." (PMID 35816477, 2022). "We developed a novel GRG signature of six GRGs, including CACNA1H, CHPF, IRS2, NT5E, SDC1 and ATP6AP1, to predict survival and guide individual therapy in breast cancer." (PMID 36277284, 2022). "A combination of 4 different miRNAs target the IRS2 and RASRGP1 genes in the MDA-MB-231 breast cancer cell line (darker purple squares)." (PMID 34157951, 2021). "Progestin stimulation prior to IGF-1 treatment of PR+ breast carcinoma cells upregulates IRS-2 expression levels and tyrosine phosphorylation, thereby enhancing downstream IRS-2-dependent signals." (PMID 19534786, 2009). "At the tissue level, a higher expression level of IGF1R but no change in IRS2 expression level was found in the negative HER2-breast cancer of patients with T2DM compared to non-diabetic counterparts." (PMID 37510134, 2023). "In breast cancer, IGF-1 regulates cell growth through stimulation of the insulin growth factor receptor (IGF-1R), which consequently phosphorylates either insulin receptor substrate-1 (IRS-1) or insulin receptor substrate-2 (IRS-2)." (PMID 35366286, 2022). "We found that the protein levels of CACNA1H, CHPF, SDC1 and ATP6AP1 were higher in breast cancer tissues compared with normal tissues, while the expression levels of IRS2 and NT5E were comparatively lower in breast cancer tissues, and the expression of them is consistent with mRNA level." (PMID 36277284, 2022). "Furthermore, miR-30a also inhibits breast cancer cell migration through inhibiting Eya2, EYA2, DTL, insulin receptor substrate 2 (IRS2), SEPT7, and Skp2 expression." (PMID 30158978, 2018). "Consistent with this, overexpression or knockdown of IRS1 and IRS2 had little or no affect upon ErbB2 action in both mouse and human mammary epithelial and breast cancer cells." (PMID 27765041, 2016). "Upon ligand binding, IGF-1R becomes auto-phosphorylated and subsequently recruits specific docking intermediates, including insulin-receptor substrate-2 (IRS-2), that activate PI3K/AKT and Ras/Raf/MAPK pathways in order to promote cell motility and pro-metastatic behaviour in breast cancer cells." (PMID 25629807, 2015). "In breast cancer, activation of the IGF-1R could result in stimulation of proliferation and metastasis through activation of insulin receptor substrate-1 and insulin receptor substrate-2." (PMID 23663564, 2013). "The main way that oestrogens potentiate the response of breast cancer cells to IGFs is probably by induction of the expression of components of the IGF signal transduction pathway including type I IGF receptor, IRS-1, and IRS-2." (PMID 23983688, 2013). "The association of IRS-2 with tumor progression was first indicated by the finding that inhibition of the IGF-1R in ER- breast carcinoma cells, which express IRS-2 and lack or have decreased IRS-1 expression, does not inhibit tumor proliferation." (PMID 19534786, 2009).
breast carcinoma (continued). "Several studies have since demonstrated that IGF-1 promotes cell motility and invasion in human breast carcinoma cell lines and mouse mammary tumor cells that signal preferentially through IRS-2, but not in cell lines that express only IRS-1." (PMID 19534786, 2009). "The different functions of IRS1 and IRS2 in breast cancer are further evidenced by the fact that mouse mammary tumors lacking IRS2 have a significantly diminished ability to metastasize to the lungs, whereas tumors lacking IRS1 but expressing elevated IRS2 have enhanced metastatic potential." (PMID 36975518, 2023). "Additionally, ATAD2 could positively mediate the expression of pro-survival genes, including SGK, VEGF, IRS2, and AKT, which contribute to promoting breast cancer progression." (PMID 36139505, 2022). "In breast cancer cells, ERα interacts with IRS1 and IRS2 independent of E2, thereby protecting against ubiquitination-induced degradation." (PMID 38649684, 2024). "Taken with our previously published reports, these data support a role for IRS-1, but not IRS-2, in IGF-stimulated growth of breast cancer cells." (PMID 17043687, 2006). "As IRS-1 and IRS-2 are thought to mediate most of the effects of IR and IGF-1R in breast cancer cells, it may be possible to disrupt this molecule without affecting normal glucose homeostasis mediated by other adapter proteins in insulin target organs." (PMID 29152592, 2017). "Processes downstream of IRS-2, but independent of PI3K, that promote breast cancer invasion have not yet been extensively investigated, and future studies examining these mechanisms may reveal novel approaches for targeting IGF-1R signaling in breast cancer." (PMID 36556357, 2022).
Hyperinsulinemia (49 papers, 2012 to 2025). An increased concentration of insulin in the blood. "Under an HFD condition, the phosphorylation levels of Akt are decreased in the PP zone due to suppressed expression of Irs2 at the transcriptional level by the hyperinsulinemia associated with DIO." (PMID 33923817, 2021). "In this context, increased SREBP1 activity was found to be associated with decreased hepatic IRS2 expression and hyperinsulinemia in obese diabetic mice." (PMID 32235829, 2020). "This may be caused by the downregulation of Irs2 induced by hyperinsulinemia in both the PP and PV zones of the liver, coupled with the higher Irs1 expression levels in the PV zone." (PMID 27708333, 2016). "Thus, insulin signaling may be decreased mainly under fasting conditions in the HF-diet group, as hyperinsulinemia associated with HF diet feeding may suppress Irs2 expression." (PMID 24284392, 2013). "This has been suggested as a contributory factor of decreased hepatic IRS-2 mRNA in chronic hyperinsulinemia." (PMID 41196673, 2025). "There was evidence of a multilayered epigenetic down-regulation of IRS-2 expression in patients with T2DM with hyperinsulinemia." (PMID 41196673, 2025). "LY294002, but not PD 0325901, blocked insulin-mediated repression of Igf1r and Irs2, further demonstrating that hyperinsulinemia reduces Igf1r through PI3K signaling." (PMID 40105689, 2025). "Liver lipase activity shows a positive correlation with intra-abdominal fat levels; thus, hyperinsulinemia correlates with insulin receptor substrate-2 (IRS-2) downregulation in the liver." (PMID 36769165, 2023). "At the same time, it also has the ability to inhibit IRS-2 (Insulin Receptor Substrate 2) phosphorylation, a protective mechanism against the onset of tissue hyperinsulinemia." (PMID 36981906, 2023). "Plasma insulin measurements confirmed hyperinsulinemia in Irs2–/–;Cdk4-R24C/R24C males, suggesting rescue of insulin secretory capacity in the context of at least some residual insulin resistance." (PMID 37712417, 2023). "The following is the specific mechanism of action: at the transcriptional level, hyperinsulinemia causes IRS1 protein degradation and inhibits IRS2 production." (PMID 36589630, 2022). "Due to the abundant expression of Irs1 in the PV zone, insulin signaling is considered to be rather enhanced in the presence of hyperinsulinemia despite the downregulation of Irs2, resulting in increased lipogenesis and development of steatosis." (PMID 33923817, 2021). "It has been reported that the downregulation of IRS-2 levels in endothelial cells is induced by hyperinsulinemia in obese subjects." (PMID 34366875, 2021). "Like the LIRKO mice, liver-specific Irs1/Irs2 double-knockout (LIrs1/2DKO) mice also exhibited impaired glucose tolerance with hyperinsulinemia and impaired suppression of hepatic glucose production." (PMID 33923817, 2021). "These increases in Akt‐dependent effects on SREBP‐1c and lipogenic enzyme expression accentuate those induced by increases in hepatic aPKC activity owing to increases in hepatic ceramide levels and hyperinsulinemia acting through IRS‐2/PI3K." (PMID 34766133, 2021). "While the plasma insulin levels were significantly reduced, the peritoneal MΦ Irs2 expression levels were significantly increased in the STZ plus phlorizin-treated mice, suggesting that hyperinsulinemia downregulates MΦ Irs2 expression in vivo." (PMID 30451856, 2018). "On the other hand, in this study, we found that hyperinsulinemia downregulated Irs2 expression, which led to impaired M2a-subtype MΦ activation." (PMID 30451856, 2018). "In T2D patients, the presence of the second-phase hyperinsulinemia, together with the flat post-peak activity of IRS2, contributes to the hyperactivity of aPKC in the liver of these patients." (PMID 29118381, 2017).